ACLY (ATP citrate lyase)
Diseases named in the same sentence as ACLY in open-access papers (continued):
Sharing a sentence is not in itself a finding about the gene and the disease.
cancer (continued). "Significant evidence suggests an important role for ACLY in the biology of gynaecological cancers, including increased ACLY expression evident in breast, ovarian and cervical cancers, parallel to the high rate of de novo FA synthesis reported therein." (PMID 35448537, 2022). "The importance of ACLY in KRas-driven cancer cells is underscored by the sensitivity of these cells to the ACLY inhibitor SB-204990." (PMID 36269753, 2022). "For example, the production of ACLY-dependent acetyl-CoA was recently found to play an important role in the early stage of pancreatic cancer development, and once cancer is formed, ACSS2 is highly expressed." (PMID 39086974, 2022). "ACLY is involved in oxaloacetate, acetyl-CoA and citrate turnover and promotes cancer cell proliferation and progression." (PMID 34941573, 2022). "In early studies, the authors demonstrated that inhibition of ACLY induces apoptosis and/or suppression of growth in a subset of cancer cells." (PMID 35178152, 2022). "As previously shown, citrate can be exported from the mitochondria to the cytosol and be converted to acetyl-CoA and oxaloacetate (OAA) by ACLY, a mechanism that is found upregulated in some types of cancer cells." (PMID 36299478, 2022). "Apart from that, other investigators have demonstrated the potential use of targeting ACLY in overcoming drug resistance in several cancer types, such as hepatocellular carcinoma and ovarian cancer." (PMID 35448537, 2022). "It has been demonstrated that ACLY has abnormal expression in various tumors (e.g., of the lung, breast, stomach, and colon), which is related to the prognosis of cancer patients." (PMID 35154461, 2022). "In various types of cancer, decreased ACLY expression reduces the viability of cancer cells and inhibits the proliferation, invasion, and migration of tumor cells." (PMID 35743814, 2022). "This formation occurs by lipogenic enzymes which are highly expressed in cancer cells and include acetyl-CoA carboxylase, fatty acid synthase, and ATP citrate lyase." (PMID 35634242, 2022). "The impact of PPARγ on cancers is complex and bidirectional, PPARγ acts as a tumor promoter by induction of lipogenic gene ACLY, MIG12, FASN, and NR1F1, stem cell-related gene KLF4, ALDH and upregulation Nox1 ROS, and VEGF." (PMID 36587194, 2022). "ACLY expression is upregulated in many cancers, including CRC, prostate cancer, bladder cancer, HCC, and GC." (PMID 36359776, 2022). "Overexpression of ACLY has been reported to be closely related to metabolic diseases such as atherosclerosis, hyperlipidemia, and cancer." (PMID 36588702, 2022). "ATP-citrate lyase (ACLY) has been reported to be abnormally high expressed in many cancers and promotes the proliferation of tumor cells." (PMID 36241648, 2022). "Through the upstream inhibition of miR-22, ACLY expression was downregulated, and more cells in cancer tissues underwent excellent differentiation." (PMID 39086974, 2022). "Elucidating the regulation mechanisms of ACLY in cancer helps people to further understand its function in cancer initiation and progression." (PMID 36241648, 2022). "In cancer cells the inactivation of SIRT6 leads to the accumulation of nuclear ACLY protein, increases the pool of nuclear acetyl-CoA, and then drives the histone acetylation and cancer invasion." (PMID 39086974, 2022). "Correspondingly, targeting ACLY with interfering RNAs decreases the proliferative capacity of ovarian cancer cells, demonstrating its critical role in supporting cancer cell growth." (PMID 35634242, 2022). "Among them, ACLY significantly promoted GC lipid metabolism and increased cancer cell proliferation, suggesting that this pathway can be targetable as a metabolic vulnerability in future GC therapy." (PMID 36064336, 2022). "ACLY, a cytoplasmic enzyme catalyzing citric acid breakdown to acetyl-CoA, was found to be overexpressed in several cancers like breast, colorectal, non-small cell lung cancers etc.." (PMID 35433453, 2022).
cancer (continued). "siRNA was used to specifically interfere with ARHGEF3 expression in H1299 and A549 cells, and the cell growth assays revealed that ectopic ACLY expression recovered cancer cell proliferation." (PMID 36241648, 2022). "A number of inhibitors targeting SCL13A5 and ACLY have been developed as potential therapeutic agents against different malignant tumours of the brain and peripheral tissues, limiting cytoplasmic acetyl-CoA synthesis." (PMID 36077475, 2022). "Previous work showed that ACLY-dependent acetyl-CoA production promotes cancer cell adhesion and migration, properties that contribute to tumor invasiveness." (PMID 34573442, 2021). "ACLY is a downstream target of SREBPs and has been found to be upregulated in a variety of cancers, including breast cancer, non-small cell lung cancer, and hepatocellular carcinoma." (PMID 34604067, 2021). "ACLY is essential for growth and proliferation of cancer cells by supporting membrane biosynthesis through de novo fatty acid synthesis." (PMID 33679780, 2021). "ACLY (the main enzyme in the conversion of citrate derived from glycolytic metabolism into acetyl-CoA) is overexpressed in many cancer cell lines that are stimulated by insulin, growth factors, and hyperglycemia." (PMID 36046117, 2021). "Here, we have characterized a functional interaction between SIRT6 and ACLY which plays essential roles in modulating nuclear acetyl-CoA abundance, locus-specific histone acetylation, and the expression of cancer cell adhesion and migration genes." (PMID 34573442, 2021). "Several studies reported that elevated ACLY expression is involved in the initiation, progression, and metastasis in many aggressive cancers by accelerating lipid synthesis and tumor progression, including CRC34,36." (PMID 34075028, 2021). "Overexpression of fatty acid biosynthetic genes such as those encoding for fatty acid synthase (FASN), ATP-citrate lyase (ACLY), and acetyl-CoA carboxylase (ACC), have been reported in tumors of various cancer types." (PMID 34770949, 2021). "ACLY is significantly upregulated in several types of cancer including liver cancer, and facilitates the proliferation and metastasis of cancer cells." (PMID 34839358, 2021). "It has also been reported that K540, K546, and K554 (NP_001087 numbering, a shorter isoform) acetylation blocks the ubiquitylation of ACLY, increasing its stability in cancer cells." (PMID 34831186, 2021). "ATP citrate lyase (ACLY), a critical enzyme in the metabolic reprogramming of many cancers, is the first rate‐limiting enzyme in the de novo synthesis of fatty acids and is widely expressed in a variety of mammalian tissues." (PMID 33393219, 2021). "Viewed from the metabolic perspective, ATP citrate lyase, a key enzyme responsible for generating cytosolic acetyl-CoA, was overexpressed in cancer cells to regulate stemness and metastasis." (PMID 34629100, 2021). "Due to its impact on cancer cell growth, ACLY is an attractive target for anti-cancer drug development efforts." (PMID 33679780, 2021). "Remarkably, cancer cells frequently upregulate ACLY, thus accelerating the transformation of citrate to sustain biosynthesis." (PMID 34205414, 2021). "ATP citrate lyase (ACLY), a key enzyme in the metabolic reprogramming of many cancers, is widely expressed in various mammalian tissues." (PMID 33393219, 2021). "ACLY has already been identified as a potential molecular target for cancer therapy, as de novo fatty acid synthesis occurs at very high rates in tumor tissues." (PMID 34048454, 2021). "ACLY plays a remarkable role in metabolic regulation in cancer cell and would be a promising target for cancer therapy." (PMID 33378581, 2021). "Recently, ATP-citrate lyase inhibition has been proposed as a potential treatment track for cancer and/or metabolic diseases." (PMID 34502162, 2021). "FASN, ACC, and ACLY are downstream target genes of the SREBPs transcription factors that are upregulated in cancer cells." (PMID 34766135, 2021).
cancer (continued). "Growing evidence highlights ACLY’s central role in giving this enzyme a strong therapeutic potential as a key target for cancer treatment." (PMID 34344378, 2021). "Together, our observations demonstrate a novel tumor suppressive mechanism of SIRT6 on cancer cell adhesion and migration through the control of ACLY-dependent gene regulation." (PMID 34573442, 2021). "For example, in cancer cells, citrate is processed by ATP citrate lyase (ACL) to produce acetyl-CoA (this molecule can be used for fatty acid production)." (PMID 31947710, 2020). "In several cancer types, the ACLY has been expressed in higher levels in comparison to normal cells and its inhibition is known to induce proliferation arrest in cancer cells both in vitro and in vivo." (PMID 32597160, 2020). "Snail, a crucial transcription factor for EMT induction, is a potential target of ACLY in the process of Ras-induced cancer stemness." (PMID 32641978, 2020). "ACLY inhibitors, previously developed for metabolic disorders, have recently attracted interest as promising anti-cancer agents." (PMID 32028963, 2020). "Increased lipid synthesis is a main character of many cancers, whereas ATP-citrate lyase (ACLY) is a key enzyme for lipid synthesis and is frequently overexpressed or activated in cancer to promote tumor progression." (PMID 33109073, 2020). "Knockdown of ACLY inhibits epithelial–mesenchymal transition, a phenomenon related to cancer stemness." (PMID 33339398, 2020). "ACLY is a key enzyme in cellular lipogenesis aberrantly expressed in many cancer types such as breast, liver, colon, lung, and prostate cancers." (PMID 32252351, 2020). "In order to better understand the roles of ACSS2 in cancer, it is helpful to compare its function to that of ATP-citrate lyase (ACLY)." (PMID 33304273, 2020). "So, ACLY is considered an anti-cancer drug target with a great therapeutic potential, and there is a great effort to develop new ACLY inhibitors or to re-evaluate those previously developed for metabolic disorders." (PMID 32666259, 2020). "Although further experiments are needed to define the molecular mechanism by which high concentrations of citrate inhibit ACLY, the results reported in this work shed light on some data in the literature regarding the use of citrate in the treatment of cancer." (PMID 33282912, 2020). "Since phospholipids are the basic units of membranes, in cancer disease different enzymes involved in their endogenous synthesis are highly expressed, such as ATP-citrate lyase (ACLY), acetyl CoA carboxylase (ACC) and fatty acid synthase (FAS)." (PMID 32854444, 2020). "Consistently, knockdown of Akt in human cancer cells leads to downregulation of ACLY, ACC, and FASN." (PMID 32947972, 2020). "ACLY expression negatively correlates with tumor stage and differentiation, and this makes ACLY a potent target for anti-cancer therapy." (PMID 32252351, 2020). "ACLY is often overexpressed in cancer, and inhibition of ACLY is known to impair tumorigenesis, and impede cancer stemness and growth." (PMID 32849657, 2020). "MICA expression was reduced by inhibitors of mitochondrial function, FCCP and etomoxir e.g., and depended on conversion of citrate to acetyl-CoA and oxaloacetate by ATP citrate lyase, which was also observed in several cancer cell types." (PMID 32849657, 2020). "Elevated level of SREBP1, one of the key transcription factors that regulate the transcription of lipogenic enzymes such as FASN and ACLY, has been found in numerous types of cancer." (PMID 31772672, 2019). "For example, ACLY-dependent acetylation was recently found to induce the expression of cell migration and adhesion genes, promoting malignant tumor formation." (PMID 30809153, 2019). "Depletion of ACLY protected cancer cells from hypoxia-induced apoptosis through modulating ETV4 via α-ketoglutarate." (PMID 31088900, 2019).
cancer (continued). "Among enzymes of the CCM, both pyruvate dehydrogenase (PDH) and ATP citrate lyase (ACL) play key role in metabolic reprogramming of cancer cells." (PMID 30816152, 2019). "Silencing ACLY suppresses cancer cell proliferation, induces stemness, and even promotes tumor cell differentiation and senescence." (PMID 31511060, 2019). "Suppression of ACLY expression reduces the population of cancer stem cells in many cell lines with a wide range of genetic differences." (PMID 30967137, 2019). "Since ACLY has been reported to be critical for cancer cell proliferation and metastasis, we next examined the effect of caspase-10 on ACLY-promoted malignant phenotype." (PMID 31534141, 2019). "In several cancer cell lines, depletion of ACLY was observed to induce apoptosis, accompanied by increased levels of ROS." (PMID 29459863, 2018). "Compared with the control group, cancer cell-derived exosomes were significantly and positively correlated with lipogenesis since the levels of ACLY, FASN and USP2a were increased in exosome-challenged HSCs." (PMID 30591064, 2018). "The processing of citrate by ACLY has also been suggested as an anti-cancer target as ACLY has been found to be overexpressed in several cancer types." (PMID 29459863, 2018). "Inhibition of ATP citrate lyase (ACLY), leads to growth suppression and apoptosis in a subset of human cancer cells." (PMID 29859541, 2018). "SB-204990, an ACLY inhibitor, reduces proliferation and survival of cancer cells, in vitro, and tumor growth and cells differentiation, in vivo." (PMID 29805774, 2018). "ACLY role in epigenetic control was initially described for cancer cells, where ACLY critically supports de novo lipogenesis and thus, cell proliferation." (PMID 30568658, 2018). "One study has suggested that the anti-cancer effect of ACLY inhibition is directly due to its role in lipid synthesis." (PMID 29459863, 2018). "Conversely, cancer cell metabolism can influence cancer stemness, as illustrated by Alessandro Carrer who reported that acetyl-CoA production by ATP-citrate lyase and subsequent histone acetylation are early events in the tumorigenesis of Kras-driven PDAC." (PMID 30338239, 2018). "ACLY is a downstream target of SREBPs, and is up-regulated in many cancers, including glioblastoma, colorectal cancer, breast cancer, non-small cell lung cancer, and hepatocellular carcinoma." (PMID 29784041, 2018). "ACLY suppression by ACLY knockdown induced an anticancer effect via reactive oxygen species in many cancer cells." (PMID 29546056, 2018). "ACLY is required for cell proliferation and cancer cell survival and there is interest in the development of ACLY inhibitors with some showing potential for inhibiting tumor growth." (PMID 29296215, 2017). "Recently, growing evidence have been provided for the prominent role of ACLY in cancer ascribed to its overwhelming metabolic activity and deregulated protein expression." (PMID 28399876, 2017). "Increased ACLY expression and activity have been noted in a number of cancers, including breast, leading to the suggestion that it is a key player in cancer metabolism." (PMID 28412757, 2017). "Inhibiting key enzymes involved in fatty acid synthesis, including FASN, ACC, and ACLY, with small molecules or knockdowns reduces cell proliferation, induces the apoptosis of cancer cells, and decreases the growth of human tumors grown as mouse xenografts." (PMID 28421159, 2017). "Recently, more and more researches have been focusing on the prominent role of ACLY in cancer owing to its overwhelming metabolic activity and deregulated protein expression." (PMID 27317765, 2016).
cancer (continued). "And the inhibition of ACLY with genetic or pharmacologic strategies promotes apoptosis and differentiation, leading to the suppressive effect in various cancers." (PMID 27317765, 2016). "Chemical or RNAi-mediated inhibition of key enzymes involved in fatty acid synthesis, including FASN, ACC and ACLY, reduces cell proliferation, induces apoptosis of cancer cells and retards the growth of human tumors in mouse xenograft models." (PMID 27223259, 2016). "ATP citrate lyase (ACLY), a key enzyme initiating de novo lipid synthesis, has been found to be upregulated in cancer cells, and its inhibition causes suppressive effects in a variety of tumors." (PMID 27317765, 2016). "Clearly, both OGDH and ACLY are essential to maintain cancer cell proliferation by maintaining lipogenic acetyl-CoA pools." (PMID 27892457, 2016). "ACLY inhibitors have been evaluated for their ability to block fatty acid synthesis and cancer cell proliferation, among which SB-204990 was shown to be effective in both in vivo and in vitro tumour models." (PMID 27892457, 2016). "Further, quantitative proteomic analysis and data from the cancer genome atlas revealed that ACLY, an enzyme key for de novo lipogenesis, was negatively correlated with ERBB4." (PMID 26701850, 2016). "Previous studies have demonstrated that ATP citrate lyase (ACLY) plays an important role in the development of many cancers." (PMID 25890184, 2015). "We discovered that genetic depletion of acetyl-CoA carboxylase (ACACA or ACC1) or ATP citrate lyase (ACLY) protected cancer cells from hypoxia-induced apoptosis." (PMID 26452058, 2015). "ACLY is upregulated in several types of cancer cells and this enzyme also plays an important role in cancer cell progression." (PMID 25826294, 2015). "Completing these screens revealed that the inhibition of ACC1 or ACLY, two key enzymes of de novo lipogenesis, protected cancer cells from hypoxia-induced apoptosis." (PMID 26452058, 2015). "By contrast, it repressed the mRNA expression of ATP citrate lyase, a cytosolic enzyme that catalyzes the generation of acetyl-CoA from citrate and is over-expressed in several types of cancers." (PMID 25834103, 2015). "All these data strongly support the idea that the ACLY is involved in the development and progression of human cancers." (PMID 25890184, 2015). "Our data provides several insights on the biological effects of ACC1 and ACLY in hypoxic cancer cells that should be considered when targeting these enzymes." (PMID 26452058, 2015). "The relative contributions of these discrete roles of ACLY in tumorigenesis need to be more clearly defined to target ACLY effectively in anti-cancer therapies." (PMID 24203995, 2013). "De novo fatty acid synthesis is a cancer therapy target and the drug Orlistat and several other drugs target the fatty acid synthase (FASN) enzyme while other cancer drugs target ATP citrate lyase (ACLY)." (PMID 24958139, 2013). "As with FASN and ACC, marked elevation of ACLY expression and activity has been reported in cancer cells." (PMID 19352381, 2009). "Also, suppressed citrate cleavage by the inhibition of ACLY leads to the decrease of acetyl-CoA and histone acetylation, resulting in the downregulation of proliferative and metastatic genes in cancer cells." (PMID 39824985, 2025). "In PCa, ACLY is overexpressed; however, when this enzyme’s expression is downregulated in PCa cells through pharmacologic agents or small interfering RNA therapy, cancer growth is reduced." (PMID 41009695, 2025). "Bempedoic acid (ETC-1002), an ACLY inhibitor, was found to induce apoptosis and inhibit cancer cell invasion, and in combination with palbociclib (a CDK4/6 inhibitor), it significantly reduced cell viability in a panel of breast and pancreatic cancer cell lines." (PMID 40723225, 2025).